CAMKK2 (calcium/calmodulin dependent protein kinase kinase 2)
Diseases named in the same sentence as CAMKK2 in open-access papers (continued):
Sharing a sentence is not in itself a finding about the gene and the disease.
tumor (continued). "Subcutaneous tumor analysis showed that the average tumors volume of the nude mice in the CAMKK2 overexpression group were significantly larger than that of the control group." (PMID 38082327, 2023). "Knockdown of Camkk2 in mice decreased the accumulation of MDSCs, enhanced the anti-tumor response of T-cells and slowed tumor growth." (PMID 37091970, 2023). "CaMKK2’s pro-tumor effects are likely mediated by multiple cell types, including immune and brain-native cells." (PMID 36309495, 2022). "One study reports high CaMKK2 expression in TNBC and shows CaMKK2 inhibition can significantly reduce tumour growth by increasing sensitivity to CTL mediated destruction." (PMID 36290817, 2022). "This implicates neuronal CaMKK2 as a key contributor to the tumor-promoting TAM phenotype, tumor progression, and ICB resistance within the GBM TME." (PMID 36309495, 2022). "Neuronal CaMKK2 has profound pro-tumor effects, demonstrated by its ability to maintain TAMs in an ICB resistance-associated phenotype, as well as promote tumor progression and ICB resistance." (PMID 36309495, 2022). "A study identified calmodulin kinase kinase 2 (Camkk2) as a target for the accumulation of MDSCs in E.G7-OVA tumor-bearing mice." (PMID 35854339, 2022). "In this work we demonstrate that neurons contribute to ICB resistance, that CaMKK2 is highly expressed in neurons and TAMs and has tumor-promoting functions in the GBM TME." (PMID 36309495, 2022). "Collectively this suggests that CaMKK2 represents a potential therapeutic target that promotes pro-tumor functions of stromal cells and is highly expressed in the GBM TME." (PMID 36309495, 2022). "Collectively these results indicate that CaMKK2 promotes tumor progression, ICB-resistance, and pro-tumor immune phenotypes." (PMID 36309495, 2022). "These experiments confirmed that there were significantly more CD4+ TILs per mm3 of tumor volume, but also that intratumoral penetrance was significantly enhanced in CaMKK2 KO mice." (PMID 36309495, 2022). "Treatment with the CAMKK2 inhibitor STO-609 decreased tumor growth in a CRPC subcutaneous xenograft mouse model, demonstrating that CAMKK2 can be pharmacologically targeted." (PMID 35741020, 2022). "CaMKK2 within the hematopoietic additionally has pro-tumor effects as evidenced by the bone marrow chimera experiments." (PMID 36309495, 2022). "The pro-tumor TIL phenotypes seem to be driven by hematopoietic CaMKK2 expression, likely as a combination of expression in innate and lymphoid cells." (PMID 36309495, 2022). "Using this approach, we identified that CaMKK2 deficiency in neurons is sufficient to induce ICB response and anti-tumor immune phenotypes." (PMID 36309495, 2022). "It has been demonstrated that inhibition of CAMKK2 in myeloid cells suppresses tumor growth by increasing intratumoral accumulation of effector CD8 + T cells and immune-stimulatory myeloid subsets." (PMID 34563205, 2021). "Herein, we demonstrate CaMKK2 expression in host cells regulates syngeneic tumor growth by controlling tumor-induced MDSCs." (PMID 34712241, 2021). "We found three-fold more IFN-γ spots in splenocytes isolated from Camkk2-/- compared to WT mice, which suggests the decrease of MDSC in Camkk2-/- mice unleashes an anti-tumor immune response that restrains tumor growth." (PMID 34712241, 2021). "The Camkk2 promoter was highly active in the Ly6Chigh/Ly6Gdim subset (M-MDSC) and CD11b+, Ly6Cdim, Ly6Gdim, F4/80+ tumor-associated macrophage-like cells (DN gate)." (PMID 34712241, 2021). "Increasing evidence documents a network of relevant bidirectional interactions among ROS and calcium signaling, and CaMKK2 has been recently identified as an important regulator of ROS accumulation and ferroptosis in tumor cells." (PMID 34712241, 2021). "The inhibition of CaMKK2 within myeloid cells suppresses tumor growth by increasing immune-stimulatory myeloid subsets and intra-tumoral accumulation of CD8+ T cells in TNBC." (PMID 34283088, 2021).
tumor (continued). "Cumulatively, these data confirmed the in vivo tumor suppression results, indicating that the deletion of Camkk2 impacts MDSC expansion, exerting only a negligible effect on MDSC immunosuppressive function." (PMID 34712241, 2021). "Translationally, we propose CaMKK2 as an important regulator of MDSCs biology, and a potential therapeutic target to stimulate the anti-tumor immune response." (PMID 34712241, 2021). "Although in our experimental conditions, the specific contribute of M- and G-MDSC subsets, these data indicate that restoring the number of MDSC was thus sufficient to revert the protective effect of Camkk2 deletion on tumor growth." (PMID 34712241, 2021). "Herein, we leveraged genetically modified models and a small molecule inhibitor to validate Calcium-Calmodulin Kinase Kinase 2 (CaMKK2) as a druggable target to control MDSC accumulation in tumor-bearing mice." (PMID 34712241, 2021). "α-KG was shown recently to activate 5′ adenosine monophosphate-activated protein kinase (AMPK) to promote anoikis resistance of tumor cells by enhancing its interaction with calcium/calmodulin-dependent protein kinase kinase 2 (CamKK2)." (PMID 32461965, 2020). "Since Camkk2 promoter activity is restricted to the myeloid lineage in tumors, it seemed likely that CaMKK2 impacted tumor growth through its ability to regulate CD8+ T cell function secondary to activities within myeloid cells." (PMID 31164648, 2019). "Under these conditions, a remarkably higher number of OTI T cells migrated through the micro-channels and infiltrated the 3D tumor chamber containing Camkk2−/− BMDM, compared with those moving toward the tumor chamber housing WT BMDM." (PMID 31164648, 2019). "Analysis of the whole-tumor lysates from Camkk2−/− mice showed a remarkable upregulation of genes expressed in the cytotoxic effector lymphocyte subsets, such as Granzyme B (Gzmb) and Perforin-1 (Prf1) (top)." (PMID 31164648, 2019). "Our data suggest that CaMKK2 is required to couple the proximal signaling events induced by tumor-derived factors present in the TCM with downstream molecular effectors." (PMID 31164648, 2019). "Treatment with CaMKK2 inhibitors blocks tumor growth in a CD8+ T cell-dependent manner, and facilitates a favorable reprogramming of the immune cell microenvironment." (PMID 31164648, 2019). "Given the positive impact of CaMKK2 inhibition by STO-609 on tumor growth, we proceeded to generate novel, chemically distinct, CaMKK2 inhibitors via a discovery campaign that led to the identification of GSK1901320 (denoted GSKi)." (PMID 31164648, 2019). "We propose that inhibition of CaMKK2 is a more selective way of inhibiting the fraction of AMPK involved in macrophage polarization while preserving the anti-tumor functions of CD8+ T cells." (PMID 31164648, 2019). "We find that deletion of CaMKK2 in myeloid cells, or its pharmacological inhibition, attenuates tumor growth in a CD8+ T cell-dependent manner, facilitating a favorable reprogramming of the immune cell microenvironment." (PMID 31164648, 2019). "Defining the specific links between CaMKK2, cholesterol, and tumor biology is a current research priority." (PMID 31164648, 2019). "Mechanistically, our studies reveal that CaMKK2 is required to link tumor-derived factor signaling with the activation of AMPK, which likely functions to impair the immune-stimulatory functions of myeloid cells within the TME44–46." (PMID 31164648, 2019). "Our findings highlight the role(s) of CaMKK2 as a myeloid-expressed regulator that integrates signals controlling activation and differentiation of macrophages in the tumor microenvironment." (PMID 31164648, 2019). "CaMKK2 intensity increased with tumor progression in a transgenic adenocarcinoma of the mouse prostate (TRAMP) mouse model of PCa, and its expression was higher in castration-resistant tumor xenografts than androgen-responsive ones." (PMID 29967592, 2018).
tumor (continued). "In fact, the activity of CaMKK2 has emerged as an important regulator of metabolic and inflammatory processes that likely contribute to its impact on tumor growth." (PMID 28924233, 2017). "For both cell lines CAMKK2 mRNA expression increased 2–3 fold with differentiation, suggesting that CAMKK2 expression is reduced in the more stem cell like tumor cells." (PMID 27171399, 2016). "Tumor cells, often overexpressing CaMKK2, are particularly sensitive to this pathway." (PMID 41036604, 2025). "Furthermore, we found increased tumor cell density in hydrogels encapsulating WT BMDMs compared to Camkk2−/− BMDMs." (PMID 40036145, 2025). "Hence, using CaMKK2 inhibitors would selectively modulate macrophage fate in stiff tissues, whereas the IL‐4‐induced macrophage polarization in non‐tumor tissues would remain unaffected." (PMID 40036145, 2025). "The results showed that the expression levels of p-β-catenin, β-catenin, and CCND1 proteins were significantly increased in tumor tissues overexpressing CAMKK2, while the expression levels of p-β-catenin, β-catenin, and CCND1 proteins were decreased in the bufalin-treated group." (PMID 38082327, 2023). "In addition, the expressions level of CAMKK2 in tumor tissues was significantly higher than in adjacent tumors." (PMID 38082327, 2023). "Tumor growth was restored in Camkk2−/− mice when transplanted with MDSCs." (PMID 37091970, 2023). "Additionally, studies have indicated that calmodulin-dependent kinase kinase 2 (CaMKK2) reduces the amplification of effector CD4 + T cells to limit the tumor penetrance of GBM patients." (PMID 37208656, 2023). "Considering the newly conferred response to ICB, a traditionally CD8+ T-cell-directed therapy, we evaluated whether T cells mediate tumor clearance in CaMKK2 KO mice." (PMID 36309495, 2022). "In contrast, the ability to restore tumor growth was restored by the overtransplantation of MDSCs into Camkk2-/- mice, suggesting the critical role of MDSCs in the tumor immunosuppressive process and a possible role of Camkk2 as a target to inhibit MDSC expansion." (PMID 35854339, 2022). "Indeed, knockdown of Camkk2 in mice resulted in an enhanced anti-tumor immune response of T cells and reduced accumulation of MDSCs, slowing down the growth of tumor cells." (PMID 35854339, 2022). "It is unknown if the tumor-extrinsic effects we observed for CAMKK2 are specific to any genetic subtypes." (PMID 35741020, 2022). "Because CaMKK2 deficiency licenses such an immunostimulatory TME landscape, we anticipate it will also synergize with other T-cell-dependent therapies, such as chimeric antigen receptor (CAR)-T cells and tumor vaccines." (PMID 36309495, 2022). "Tumors in Pb-Cre4;Ptenf/f mice may be less sensitive to insulin/tumor-extrinsic CAMKK2 functions since there is already high basal mTOR signaling." (PMID 35741020, 2022). "Indeed, CaMKK2−/− (CaMKK2 KO) mice survived significantly longer than wildtype (WT) mice implanted with three separate GBM tumor models: CT2a, GL261, and KR148B-Luc (Kluc)." (PMID 36309495, 2022). "This work has translational implications for how CaMKK2 inhibition may be particularly efficacious in GBM due to the abundance of cells with pro-tumor functions which highly express CaMKK2, like neurons and TAMs." (PMID 36309495, 2022). "Neuronal CaMKK2 may indirectly influence immunosuppression via supporting tumor growth through the secretion of CaMKK2-dependent mitogenic factors such as BDNF." (PMID 36309495, 2022). "Additionally, unlike vehicle‐treated castrated samples, IVM‐treated samples demonstrated reduced PSA levels, tumor growth, p‐CAMKK2/p‐p38/p‐Hsp27 axis activity, and AR levels compared with pre‐castration samples." (PMID 33709547, 2021). "We thus hypothesized that CaMKK2 regulates myeloid cell responsiveness to tumor-derived factors, and inhibition of this kinase in host cells prevents the tumor-induced MDSC expansion." (PMID 34712241, 2021).
tumor (continued). "However, even in the conditions of increased tumor cell input, we found that deletion of CaMKK2 in the host cells effectively suppressed syngeneic tumor cell growth." (PMID 34712241, 2021). "Calcium/calmodulin-dependent kinase (CaMKK2), expressed in tumor-related stromal cells, could promote tumor growth." (PMID 34283088, 2021). "To test this hypothesis, we determined the effect of Camkk2 deletion on MDSCs accumulating in the spleen of normal and tumor-bearing mice." (PMID 34712241, 2021). "Hence, CaMKK2 is an important druggable target of therapies aimed to counteract tumor-induced immunosuppression and foster the anti-tumor immune response." (PMID 34712241, 2021). "The selective expression of CaMKK2 in the myeloid subsets makes this protein an attractive immunotherapeutic target whose inhibition is expected to remodel the tumor microenvironment and stimulate anti-tumor immune responses." (PMID 31164648, 2019). "The competitive ability of tumor chambers containing WT and Camkk2−/− BMDM was evaluated over a period of 72 h by wide-field imaging analysis of the entire microfluidic device, and the total number of OTI T cells within the microchannels and tumor chambers was quantified." (PMID 31164648, 2019). "The extent to which the decreased tumor growth observed in Camkk2−/− mice could be attributed to the increased number of cytotoxic T cells within these tumors was next evaluated." (PMID 31164648, 2019). "Indeed, CaMKK2 is a significant contributor to AMPK activation in specific contexts, particularly in neurons, but also in LKB1-deficient tumour cells." (PMID 29907081, 2018). "Furthermore, CaMKK2 is significantly overexpressed in multiple tumor types and knockdown or inhibition of CaMKK2 reduced cell proliferation and tumorigenicity in vivo." (PMID 28924233, 2017). "One possibility could be that the low availability of growth factors in the hypoxic tumour environment was insufficient for complete activation of the PI3K pathway, so CAMKK2 was an alternative way to compensate and sustain tumour growth." (PMID 29064423, 2017). "By comparing normal and tumor tissue we could show that two of the genes—CAMKK2 and P2RX7, were affected at the level of gene expression and protein structure, respectively." (PMID 27171399, 2016). "However, in this context, CAMKK2 promoted an immune-suppressive tumor microenvironment that could be reversed in germline Camkk2 knockout or STO-609-treated mice." (PMID 40945690, 2025). "Therefore, CAMKK2 represents a CAF-specific kinase vulnerability which may have therapeutic relevance in inhibiting tumor-CAF crosstalk." (PMID 39221276, 2024). "Indeed, our bone marrow chimera data indicate that hematopoietic CaMKK2 deficiency becomes relevant in the context of non-hematopoietic CaMKK2 deficiency in terms of impacting tumor progression." (PMID 36309495, 2022). "Furthermore, direct interaction of the tumor cells with osteoblasts occurs, and CaMKK2 in osteoblasts, osteoclasts, and macrophages signals to remodel the bone tissue after exerting multiple actions affecting the microenvironment that facilitate the establishment of metastatic foci." (PMID 31991573, 2020). "Our findings further demonstrated that deletion of Camkk2 in BMDM also results in increased expression of genes encoding CXCL9 and CXCL10 chemokines that attract and activate CXCR3 expressing cells, including Th1, CD8+ T cells, and NK cells, which positively regulate anti-tumor immunity." (PMID 31164648, 2019). "EO771 tumor cells expressing a bioluminescent reporter gene (EO771‐Luc) were thus inoculated in the tail vein of WT and Camkk2−/− mice, and the whole‐body metastatic burden was monitored by bioluminescence." (PMID 40036145, 2025). "Subsequent immunohistochemistry (IHC) staining of the xenografted tumor tissues demonstrated that shGGH effectively knocked down GGH expression, suppressed p62 level, and promoted p-AMPK and p-CAMKK2 levels." (PMID 40268350, 2025).
tumor (continued). "AMPK (CAMKK2, CREBs, PPP2R5A/B, PPP2RC/D) and cAMP (BAD, PLN) pathways regulate energy balance and induce autophagy and apoptosis, inhibiting tumour cell growth." (PMID 41007296, 2025). "We also observed that tumor cells were more proliferative in the presence of WT BMDM, with a ≈10% higher Ki67 index than Camkk2−/− BMDMs." (PMID 40036145, 2025). "CaMKK2 promotes exhaustion in CD8+ T cells and reduces the expansion of effector CD4+ T cells, additionally limiting their tumor penetrance." (PMID 36309495, 2022). "Accordingly, CaMKK2 is critical for brain-derived neurotrophic factor (BDNF) expression in neurons, which has already been seen to contribute to pro-tumor mitogenic functions in high-grade gliomas." (PMID 36309495, 2022). "Using CaMKK2-EGFP reporter mice, we confirmed that CaMKK2 is most highly expressed in TAMs and neurons in naïve and tumor-bearing mice." (PMID 36309495, 2022). "Cell–cell interaction analysis also provides insights into those interactions that are enriched in CaMKK2 KO mice, to help identify biomarkers and mechanistic determinants of ICB responsiveness and anti-tumor function." (PMID 36309495, 2022). "CaMKK2 is highly expressed in macrophages and neurons, both of which are abundant stromal cells in GBM and possess pro-tumor function." (PMID 36309495, 2022). "Mechanistically we show that the CaMKK2-AMPK axis controls the survival and the terminal differentiation of tumor-induced MDSCs by fine-tuning the accumulation of reactive oxygen species (ROS)." (PMID 34712241, 2021). "The adoptive transfer of MDSC was sufficient to restore the ability of the tumor to grow in Camkk2-/- mice, confirming the key role of MDSC in the mechanism of tumor rejection." (PMID 34712241, 2021). "Translationally, these results identify CaMKK2 as a novel druggable target to restrain MDSC expansion and enhance the efficacy of anti-tumor immunotherapy." (PMID 34712241, 2021). "The GDH1 product alpha-ketoglutarate activates calcium/calmodulin-dependent protein kinase kinase 2 (CamKK2) and activates AMPK contributing to anoikis resistance and tumor metastasis." (PMID 32516941, 2020). "In line with our previous observations, the tumor markers AMACR, CAMKK2, TMEFF2, REPS2 and ABCC4 were significantly expressed in AMACR high cells as compared to AMACR low cells." (PMID 25514598, 2015). "Next, 200 cells from the high and low gate were sorted for qPCR analysis for a subset of tumor markers such as AMACR, CAMKK2, TMEFF2, REPS2 and ABCC4." (PMID 25514598, 2015). "This, in turn, suggests that CaMKK2 may restrict the abundance of CD40L+ IFNγ+ TNFa+ effector CD4+ TILs, the density of CD4+ cells per mm3 of tumor volume, and the tumor penetrance of CD4+ T cells." (PMID 36309495, 2022). "Because CaMKK2 appears to have pro-tumor functions in human GBM, and deletion of CaMKK2 extends survival in preclinical models, we expect that a brain penetrant CaMKK2 inhibitor may be efficacious as a monotherapy." (PMID 36309495, 2022). "We hypothesize that neuronal CaMKK2 is a primary driver of ICB-resistance via maintaining TAMs, an abundant component of the GBM TME, in a pro-tumor phenotype." (PMID 36309495, 2022). "As the number of tumor-infiltrating lymphoid and myeloid cells were not significantly altered in CaMKK2 KO GBM-bearing mice, we investigated the contribution of CaMMK2 to tumor-infiltrating immune cell phenotypes." (PMID 36309495, 2022). "Additionally, tumor weight trended lower and CC3 staining trended higher in Camkk2 KO mice, suggesting that KO CRPC tumors grew slower and were more necrotic." (PMID 35741020, 2022). "Importantly, genetic ablation of CaMKK2, or its pharmacological inhibition led to accumulation of less immune-suppressive myeloid cells and more activated CD8+ T cells in the tumor microenvironment, which results in tumor growth inhibition." (PMID 31164648, 2019).